WASH2P (WASP family homolog 2, pseudogene)
Description:
Acts as a nucleation-promoting factor at the surface of endosomes, where it recruits and activates the Arp2/3 complex to induce actin polymerization, playing a key role in the fission of tubules that serve as transport intermediates during endosome sorting. Involved in endocytic trafficking of EGF. Involved in transferrin receptor recycling. Regulates the trafficking of endosomal alpha5beta1 integrin to the plasma membrane and involved in invasive cell migration. In T-cells involved in endosome-to-membrane recycling of receptors including T-cell receptor (TCR), CD28 and ITGAL; proposed to be implicated in T-cell proliferation and effector function. In dendritic cells involved in endosome-to-membrane recycling of major histocompatibility complex (MHC) class II probably involving retromer and subsequently allowing antigen sampling, loading and presentation during T-cell activation. Involved in Arp2/3 complex-dependent actin assembly driving Salmonella typhimurium invasion independent of ruffling. Involved in the exocytosis of MMP14 leading to matrix remodeling during invasive migration and implicating late endosome-to-plasma membrane tubular connections and cooperation with the exocyst complex. Involved in negative regulation of autophagy independently from its role in endosomal sorting by inhibiting BECN1 ubiquitination to inactivate PIK3C3/Vps34 activity (By similarity).
Synonyms: MGC52000; formerly FAM39B
Gene: Transcribed unprocessed pseudogene on chromosome 2 (113,588,550 to 113,599,034, forward strand). Ensembl gene ENSG00000146556.
Subcellular location: Early endosome membrane; Recycling endosome membrane; Late endosome; Cytoplasmic vesicle, autophagosome; Cytoplasm, cytoskeleton, microtubule organizing center, centrosome, centriole